IL10 (interleukin 10)
Diseases named in the same sentence as IL10 in open-access papers (continued):
Sharing a sentence is not in itself a finding about the gene and the disease.
Obesity (continued). "Study the possible relationship of miR-27a, miR-27b, miR-143 and miR-145 with leptin, leptin receptors, IGF1 and IL10 is important to try to understand the changes that occur in obesity and its physiopathology." (PMID 24690978, 2014). "Up to 35% of plasma IL-6 originates from adipose tissue, and other cytokines such as IL-10 and TNF-α are also reported to be elevated in obesity and linked to a wide range of metabolic complications." (PMID 23951156, 2013). "Based upon our earlier work, and that of others, we postulated that probiotic organisms such as L reuteri protected from obesity by IL-10-mediated induction of lymphocytes." (PMID 23874682, 2013). "There is growing evidence linking IL10 to obesity, metabolic syndrome (MetS) and cardiovascular disease." (PMID 23941335, 2013). "In adults, IL10 plays a protective role against the development of obesity-related declines in health." (PMID 23941335, 2013). "An elevated level of interleukin-10, an anti-inflammatory cytokine, is commonly found in obesity to counteract the effects of inflammatory cytokines." (PMID 22533381, 2012). "We previously reported that HF-induced obesity led to reduced synthesis of IL-10 from the spleen, and that systemic administration of IL-10 suppressed SPX-induced insulin resistance and the reduction in serum adiponectin levels." (PMID 23285260, 2012). "To characterize the impact of spleen-derived IL-10 on macrophage polarization in obesity-related pancreatic damage, we analyzed the pancreatic expression of a panel of M1 and M2 macrophage markers in the present study." (PMID 23285260, 2012). "As a matter of fact, IL-10 has been found decreased in obesity, metabolic syndrome and type 2 diabetes." (PMID 23300769, 2012). "The data from the present study demonstrate that obesity reduces IL-10 expression in the spleen, and that spleen-derived IL-10 protects against obesity-induced inflammatory responses in the pancreas." (PMID 23285260, 2012). "Taken together, these findings indicate that the decline in spleen-derived IL-10 observed with obesity or SPX likely promotes pathologic abnormalities in the pancreas." (PMID 23285260, 2012). "Obesity reflects ageneralized proinflammatory state with its increased inflammatorymarkers like C reactive protein, IL-6, IL-8, IL-10, PAI-1,TNF-α, and hepatocyte growth factor." (PMID 21991518, 2011). "Similarly, IL‐10 expression, an anti‐inflammatory cytokine, was suppressed by obesity, while IL‐4 levels remained unchanged across groups." (PMID 41549510, 2026). "Conversely, obesity induces Treg expansion and elevated interleukin 10, which may indirectly promote tumor immune escape by suppressing the cytotoxic functions of CD8+ T cells and natural killer cells, thereby counteracting the influence of HT on PTC." (PMID 41494178, 2026). "In addition, higher levels of IFN-γ/IL-10 and TNF-α/IL-10 ratios were found in the G2 group (older men) with obesity than in the G1 group (older men) with normal weight." (PMID 41602164, 2026). "Additionally, TBARS, IL-8, IL-10, and CRP were identified as independent risk factors for obesity, where vitamin D was identified as an independent protective factor." (PMID 42213218, 2026). "In addition, serum levels of IL-10 were higher in the G2 group (older women and older men) with obesity than in the G2 group (older women and older men) with normal weight." (PMID 41602164, 2026). "Statistically, the concentrations of GROα, IL-2, IL-4, IL-6, IL-17A, IL-22, IL-23, and MCP-3 were significantly higher in males with obesity compared to the females with obesity, while the concentrations of IL-5, IL-10, IL-18, MCP-1, and MIP2α trended higher (p ≤ 0.1)." (PMID 41488663, 2025). "On the contrary, IL-10—an anti-inflammatory cytokine—is reduced in obesity." (PMID 40002337, 2025). "Pro-inflammatory cytokines (IL-1β, IL-6, TNF) surge while IL-10 drops in obesity." (PMID 41562075, 2025).
Obesity (continued). "In contrast to our results, several human studies have associated high IL-10 levels with negative outcomes, particularly in pathological states like ovarian hyperstimulation syndrome and obesity, or have reported lower IL-10 levels in women who achieved pregnancy." (PMID 41373524, 2025). "Clinical reviews further document an increased IL-10/TNF-α ratio in obesity as a homeostatic brake on inflammation, and inflamed adipose depots concurrently express other anti-inflammatory mediators (e.g., IL-19), underscoring the shift away from TNF-α secretion in advanced adiposity." (PMID 40559392, 2025). "Specifically, it downregulates pro-inflammatory cytokines (e.g., TNF-α, IL-1β, and IL-6) while upregulating anti-inflammatory IL-10 and tight junction proteins (e.g., ZO-1 and OCLN), thereby reducing systemic inflammation and metabolic endotoxemia associated with obesity." (PMID 41365537, 2025). "In studies of obesity, levels of IL-10 were found to be elevated in individuals with obesity." (PMID 40637163, 2025). "Similarly, obesity was linked with higher TNF-α and oxidative stress markers, adipocytokines and increased IL-6, IL-8 and IL-10 in some studies." (PMID 40076848, 2025). "Additionally, HIIT has been found to regulate the levels of certain serum inflammatory markers (TNF-α, IL-10, neutrophil-to-lymphocyte ratio, neutrophil-to-monocyte ratio) in older adults with various conditions such as heart failure, obesity, and sarcopenia." (PMID 40413509, 2025). "In rats with obesity induced by monosodium glutamate, an elevation of proinflammatory cytokines IL-1β and IL-12B p40 was registered, coupled with downregulation of the anti-inflammatory system, as evidenced by reduced IL-4, IL-10, and TGF-β levels." (PMID 40259921, 2025). "Previous studies have reported that IL-10 levels are negatively correlated with insulin resistance and positively correlated with insulin sensitivity, suggesting that higher IL-10 concentrations contribute to improved metabolic regulation in individuals with obesity." (PMID 41367390, 2025). "For example, obesity, inflammaging, cardiovascular disease, hypertension, and rheumatoid arthritis are characterized by elevated concentrations of circulating cytokines, such as IL-1b, IL-6, IL-8, IL-10, IL-13, TNF-α, and IFN-γ." (PMID 39408907, 2024). "Being inversely correlated with obesity and visceral adiposity, adiponectin supports interleukin 10 (IL-10) expression and inhibits the nuclear factor kappa light-chain-enhancer of activated B cells (NFκB), influencing interferon gamma (IFNγ) production in monocyte-derived cells." (PMID 39518420, 2024). "IL-10 is an anti-inflammatory cytokine that could prevent diet-induced obesity and suppress inflammatory responses." (PMID 39206310, 2024). "Higher levels of IL-1β (A, p < 0.0001), IL-6 (B, p < 0.0001), IP-10 (E, p < 0.001), GM-CSF (F, p < 0.0001), TNF-α (G, p < 0.0001), and IFN-γ (H, p < 0.0001), and lower IL-10 levels (I, p < 0.05) were found in the volunteers with obesity compared with the NW group." (PMID 39125408, 2024). "Diet-induced obesity in mice reduces IL-10 expression in AT B cells." (PMID 38455510, 2024). "Obesity in EMS is intricately linked to persistent inflammatory states, a connection underscored by our observation of reduced pro-inflammatory markers IL-1β and TNF-α alongside an elevation in the anti-inflammatory cytokine IL-10 within the serum." (PMID 38689728, 2024). "Additionally, both galectin-1 and galectin-3 were associated with IL-10 and TNF signaling, pathways previously related to galectins and with a role in obesity-related inflammation and lipid metabolism." (PMID 38777863, 2024). "In addition, overweightness and obesity in children have been associated with elevated IL-6, CRP, and MCP-1, and CRP has been positively correlated with MCP-1, IL-6, and IL-10." (PMID 38396489, 2024).
Obesity (continued). "TNF-α was significantly elevated in MCR independent of sarcopenia but without obesity, while low IL-10 levels and IL-10/TNF-α ratio were associated with MCR, independent of sarcopenia and body composition." (PMID 38337499, 2024). "Indeed, the mRNA expression levels of Mcp1, Saa3, Haptoglobin, and Il10 exhibited a significant increase with the combined influence of aging and obesity, thus confirming the individual impacts of age and diet across all experimental groups." (PMID 39009694, 2024). "Research indicates that obesity significantly induces the production of pro-inflammatory adipokines, while adipose tissue secretes corresponding anti-inflammatory cytokines (such as IL-4, IL-10, IL-13, IL-19)." (PMID 38138996, 2023). "Lower IL-10 levels are related to obesity and metabolic disorders." (PMID 36677054, 2023). "Other factors can influence hepcidin level in obesity, such as IL-10, IL-1β and miRNA-122." (PMID 38140340, 2023). "B/F reduced in the obese mice, while partially corrected by oligofructose; Serum LPS and macrophage increased in the colon of obese mice, while reduced by oligofructose; IL-12 and MCP-1 reduced, IL-10 increased by oligofructose; oligofructose alleviated obesity-related cartilage degeneration." (PMID 37180142, 2023). "A study investigating the participation of IL-10 in an experimental model of steatosis suggested that CCR7+ mononuclear cells in the liver could regulate obesity-induced hepatic steatosis via the induction of IL-10-expressing invariant natural killer T cells." (PMID 37336969, 2023). "In our sample, IL-10 was very low in concentration (~90% < 1.0 pg/mL), which may be due to obesity, as some other studies have exhibited comparable IL-10 concentrations among youth with obesity compared to normal weight." (PMID 37299403, 2023). "It is suggested that the down-regulatory effect of IL-10 on obesity-induced chronic systemic inflammation might play a role in terms of nephroprotection." (PMID 37630806, 2023). "Although IL-10 is mostly negatively correlated with obesity, the AT of obese individuals exhibits increased IL-10 production, which may serve to regulate the inflammatory state." (PMID 37334370, 2023). "Moreover, obesity reduces the anti-inflammatory cytokine interleukin-10 (IL-10), which can contribute to FP." (PMID 37835570, 2023). "After adjusting for sex, age, hypertension, blood lipid concentration, and obesity, the analysis of covariance revealed that the levels of IL-10, IL-4, and TNF-α in the case group were significantly higher than those in the control group (P < 0.001, P = 0.011, and P < 0.001, respectively)." (PMID 36160136, 2022). "Thus, we also weighed the fat (subcutaneous and epididymal white adipose tissues) and liver tissues to investigate the effects of IL10-MSCs on obesity after the mice were killed at week 14 post-HFD feeding." (PMID 35715850, 2022). "Notably, the liposome-mediated delivery of IL-10 into macrophages results in significant anti-obesity and anti-inflammatory effects, including a marked reduction in epididymal white AT, liver steatosis, and AT inflammation in HFD-fed mice." (PMID 35909571, 2022). "In this study, we demonstrate that although WAT IL-10 levels are similar in non-obese men and women, T2D in combination with obesity is linked to a marked increase in IL-10 in scWAT of women, but not men." (PMID 36313784, 2022). "Considering that both cell lines are directly influenced by the inflammatory state that is observed in obesity, the assessment of the expression of pro-inflammatory cytokines, namely, IL-1β and IL-6, as well as anti-inflammatory cytokines, such as IL-10, was critical." (PMID 35741327, 2022). "Lean adipose tissue is rich in type 2 macrophages and anti-inflammatory cytokines such as IL10, obesity changes the balance in favour of a pro-inflammatory milieu, which can lead to the development of insulin resistance and the dysregulation of systemic metabolism." (PMID 35205336, 2022).
Obesity (continued). "Thus, MSCs are especially suitable as carriers for delivering desired key target proteins such as IL10 or other anti-inflammatory factors which are potentially beneficial to treat obesity and its related metabolic diseases." (PMID 35715850, 2022). "Adipose tissue macrophages (ATMs) infiltrate adipose tissue in obesity, and M1-activated cells secrete an array of proinflammatory cytokines that drive insulin resistance, while M2-cells promote insulin sensitivity through Il-10 signaling." (PMID 35957819, 2022). "Pro-inflammatory cytokines, such as TNF-α and IL-6, could contribute to systemic insulin resistance or metabolic disorder in obesity, while anti-inflammatory cytokines, such as IL-10 and IL-4, could prevent diet-induced obesity and insulin resistance." (PMID 35807812, 2022). "Anti-inflammatory cytokines like IL-10 are also regulated by obesity." (PMID 36313784, 2022). "In visWAT, IL10 did not correlate with HOMA-IR neither in men nor in women, whereas scWAT IL-10 had a trend towards a positive correlation (p=0.096) in women and but not in men indicating that the sex specific regulation of IL-10 in obesity/T2D is only attributed to scWAT." (PMID 36313784, 2022). "Moreover, in vivo IL-10 treatment promotes M2 macrophage polarization in the epididymal white AT of obese mice and therefore attenuates obesity-induced inflammation." (PMID 35909571, 2022). "What is more the current scientific reports suggest that IL-10 could have a protective effect in the obesity-related development of insulin resistance in some tissue, including skeletal muscle." (PMID 35205339, 2022). "Also, obesity‐related leptin level not only decreased IL‐10 production by CD4+ T cells, but also reduced the in vitro suppressive function of these lymphocytes from lean and obese AA patients." (PMID 35734271, 2022). "Some of the studies indicate polymorphisms in IL10 and IL10RB genes as associated with obesity." (PMID 35205336, 2022). "IL-10 improves age-related inflammation, obesity, and oxidative stress in skeletal muscle." (PMID 35250869, 2022). "Interestingly, TGF‐β, a cytokine that along with IL‐6 is important for the Th17 development, is more frequently expressed in the leukocytes of children with obesity and has an inverse relationship with IL‐10 in neutrophils of children with obesity." (PMID 35837843, 2022). "A higher level of IL10 expression was observed in obesity and insulin resistance subjects." (PMID 35205339, 2022). "Reported results regarding the relationship between IL10 and obesity are conflicting." (PMID 35205336, 2022). "The increased levels of IL-10 and IL-13 and decreased levels of IL-5 might be involved in maintaining immune tolerance during the initial stage of obesity, but later, might indirectly support M1 macrophage function to maintain chronic inflammation." (PMID 35456006, 2022). "To investigate whether IL10-MSCs treatments could regulate the adipocytes hypertrophy to relieve the HFD-induced obesity, we isolated mouse epididymis and subcutaneous adipose tissues and performed H&E staining." (PMID 35715850, 2022). "In contrast, circulating IL-10 levels were mostly affected (reduced) in men with obesity and T2D." (PMID 36313784, 2022). "Furthermore, after adjusting for sex, age, hypertension, obesity, and IL-10, IL-4, and IL-6 levels, an increased TNF-α level was also significantly associated with sarcopenia." (PMID 36160136, 2022). "In particular, OTU479 and OUT545 were significantly positively correlated with the percent of epididymal fat weight, TG, TC, LDL and TNF-α, and negatively correlated with IL-10, and IL-4 levels, revealing that their changes were closely connected with changed obesity in rats." (PMID 35807812, 2022). "Some reports indicated that IL10 correlates negatively with obesity and diabetes." (PMID 35955698, 2022).
Obesity (continued). "In this regard, IL-10-producing B cells have been found to reside in subcutaneous and visceral adipose tissues from mice and humans; in diet-induced obesity models, they contribute to the restriction of local inflammation and thereby control insulin resistance." (PMID 33995344, 2021). "Moreover, metabolic syndrome and obesity are related to increased pro-inflammatory and decreased anti-inflammatory cytokines’ levels, including IL-4 and IL-10." (PMID 34199832, 2021). "Moreover, due to the transformation of M2 macrophages to M1 in obesity tissues, the expression of anti-inflammatory cytokines IL-10 and IL-4 secreted by M2 macrophages is decreased." (PMID 34194325, 2021). "A study of Australian scholars indicated that obesity reduced the local IL-10 level in the mammary fat pad of ovariectomized mice, and the reduced IL-10 enhanced the expression of aromatase in mammary fad in ovariectomized mice, contributing to BC development and progression." (PMID 34350120, 2021). "Following exercise, IL-6 circulating levels increase and stimulate the IL-10 anti-inflammatory cytokine, and finally, inflammatory cytokines may act as a response to prevent obesity by modulating both energy intake and consumption." (PMID 33997019, 2021). "Interestingly, the blockage of Fas signaling can attenuate obesity-induced adipose tissue inflammation by inhibiting IL-6 whilst promoting IL-10 secretion." (PMID 33808960, 2021). "However, individuals with pathological conditions, such as obesity, reveal elevated IL-10 basal levels." (PMID 33917916, 2021). "Taken together, our data strongly support our hypothesis that it is Treg-secreted IL-10, driven by Blimp-1 expression, that suppresses adipocyte beiging and potentiates IR in obesity." (PMID 33351782, 2021). "Moreover, previous research has suggested that obesity leads to a decrease in the splenic synthesis of anti-inflammatory factors interleukin-10 (IL-10) by promoting oxidative stress." (PMID 34681487, 2021). "Furthermore, the expression of IL-10 has been reported to be reduced in obesity, metabolic syndrome and type 2 diabetes." (PMID 34322094, 2021). "Obesity is hypothesized to suppress the synthesis of IL10, resulting in chronic inflammation in WAT." (PMID 34248663, 2021). "Even though, IL-10 is known to be closely associated with obesity-related inflammation, the effect of IL-10 deficiency in obesity-related renal failure has not been investigated intensively." (PMID 33547567, 2021). "Of note, reduced serum IL-10 levels are observed in patients with obesity-driven T2D." (PMID 35822048, 2021). "As a result, obesity is associated with a low-grade chronic inflammation characterized by an increase in proinflammatory cytokines (IL-6, TNF-α, IL-1α) and a reduction in anti-inflammatory cytokines (IL-4, IL-10, and IL-13)." (PMID 34439950, 2021). "Five variables were selected automatically in a forward stepwise manner: the IL-10 level (>26.0 pg/mL), diabetes, the IL-12 (p70) level (>0.91 pg/mL), obesity, and significant lung involvement on admission (oxygen saturation ≤ 93% or >50% lung involvement on CT)." (PMID 34386533, 2021). "Obesity is also associated with alterations in multiple types of immunoregulatory cells and mediators, including Tregs, Bregs, MDSC, anti-inflammatory macrophages and IL-10." (PMID 35822048, 2021). "A study that investigated obesity-related NAFLD found that CD8+ T cells regulate obesity and hyperlipidemia-associated NASH through the production of cytokines, such as IL-10 and TNFα, which drive the recruitment of macrophages and activation of hepatic stellate cells (HSCs)." (PMID 34830072, 2021). "Similarly, in a cohort of patients with obesity, IL-10 positivity correlates with indices of insulin resistance." (PMID 33753887, 2021). "M2-related anti-inflammatory cytokine such as IL-10 in EAT might act as a compensatory mechanism involving the insulin-signaling pathway to maintain glucose homeostasis in obesity." (PMID 34266493, 2021).